SKA3 (spindle and kinetochore associated complex subunit 3)
Diseases named in the same sentence as SKA3 in open-access papers (continued):
Sharing a sentence is not in itself a finding about the gene and the disease.
tumor (continued). "In SKA3 knockdown groups, tumor cells were slower than the control cells in closing the wound at 24 h (P < 0.05)." (PMID 31804459, 2019). "The tumor volume was significantly increased in mice injected with HeLa cells stably overexpressing SKA3 from week 2 to week 6, whereas SKA3 knockdown inhibited tumor growth (vs. control vector, *p < 0.05, **p < 0.01)." (PMID 30459531, 2018). "The recurrent ASE genes in tumor samples include Chromosome-Associated Kinesin KIF4B, spindle and kinetochore associated complex subunit 3 (SKA3) and so on." (PMID 30538721, 2018). "SKA1 and SKA3 expression levels were significantly increased in the more advance tumor stage and histological grade." (PMID 29928475, 2018). "Expression of CDK4 and cyclin D1 was increased in tumor sections with SKA3 overexpression (vs. control vector, **p < 0.01) but decreased in tumor sections with SKA3 knockdown." (PMID 30459531, 2018). "Consequently, the hypoxic tumor microenvironment promoted SKA3 upregulation through HIF-1α-mediated transcriptional activation." (PMID 41298345, 2025). "In vivo experiments showed that silencing SKA3 inhibited tumor growth and peritoneal metastasis." (PMID 35295342, 2022). "Interestingly, the overexpression of SKA3 indicated a poor prognosis and an oncogene for a variety of tumor recurrence and metastasis." (PMID 34993016, 2021). "However, SKA3 was significantly upregulated in the tumor tissues of NMIBC patients who had progressed to MIBC compared to those without progression (p < 0.05)." (PMID 34572901, 2021). "So, we speculated that high expression levels of SKA1 and SKA3, to some extent, may mediate tumor escape and inhibit the infiltration levels of immune cells." (PMID 33224872, 2020). "While SKA3 silencing retarded, SKA3 overexpression accelerated tumor growth." (PMID 33106477, 2020). "Next, we aimed to investigate the function of SKA3 in CC, and the results suggested that SKA3 overexpression promotes HeLa cell proliferation, clone formation, migration and cell cycle progression and accelerates tumor growth in vivo." (PMID 30459531, 2018). "Our results suggest that SKA3 overexpression accelerates tumor growth and may serve as a predictor of poor prognosis in CC." (PMID 30459531, 2018). "Our results showed that SKA3 overexpression significantly increased xenograft tumor growth." (PMID 30459531, 2018). "SKA3 overexpression promoted cell proliferation and migration and accelerated tumor growth." (PMID 30459531, 2018). "Many more tumor tissues had high SKA3 levels than had 13q and SKA3 gene amplification." (PMID 27329586, 2016). "Additionally, SKA3 plays a role in regulating tumor cell metabolism." (PMID 41298345, 2025). "In addition, Nile red staining showed that SKA3 overexpression increased triglyceride levels in tumours, which could be reversed by PARP1 and HIF-1a knockdown." (PMID 37821935, 2023). "However, the mechanism of SKA3 regulating tumor proliferation via reprogramming metabolism is unknown." (PMID 33106477, 2020). "A SKA3-stable knockdown LM3 cell line was constructed using lentiviruses carrying shRNA to detect whether SKA3 expression levels have an impact on tumor progression in vivo." (PMID 31804459, 2019). "Thus, we demonstrated SKA3 accelerates CC tumor growth in vivo." (PMID 30459531, 2018).
tumor (continued). "Based on these findings, SKA3-mediated HIF-1α stabilization enhanced glycolysis, enabling tumor cells to tolerate hypoxia and thereby promoting liver metastasis in LUAD." (PMID 41298345, 2025). "Analysis of the tumor characteristics of the patients suggested that SKA1 and SKA3 overexpression was correlated with the IDH status and patient age." (PMID 35095717, 2021). "In the HCC patient tumor tissues, as well as GEO (GSE6764, GSE36376, GSE45436, and GSE62232) and TCGA datasets analyzed in this study, significant upregulation of SKA3 was detected, indicating poor prognosis." (PMID 31804459, 2019). "Real-time PCR was performed on 105 pairs of fresh tumor tissues and adjacent normal liver tissues (ANLT), and the result confirmed the upregulation of SKA3 in HCC tissues." (PMID 31804459, 2019). "The results of this study indicated that circ‐SKA3 and circ‐DTL were essential in tumor cell proliferation, migration, and invasion through regulating the expression of the host genes." (PMID 30402980, 2018). "Considering that high expression of SKA3 was negatively correlated with “early estrogen response” in the GSEA, it strongly further suggested that SKA3 overexpression might contribute to tumor progression by inhibiting estrogen response early in BC." (PMID 34993016, 2021). "To determine whether SKA3 expression is a potential prognostic biomarker for NMIBC patients, we measured it by qPCR in tumor tissues from 89 NMIBC patients and in 16 normal bladder tissues." (PMID 34572901, 2021). "Furthermore, there existed strong co-expression of SKA genes not only in the normal dataset of GTEx but also in tumor datasets of TCGA and GSE62452, especially the correlation between SKA1 and SKA3 (r = 0.62, 0.6, and 0.69)." (PMID 33224872, 2020). "This study supposed that upregulated circ‐SKA3 and circ‐DTL might promote tumor cell proliferation and survival, migration capacity, and invasion ability in MB cells." (PMID 30402980, 2018). "Interestingly, the effect of Si‐circ‐SKA3 or Si‐circ‐DTL on the migration and invasion of tumor cells was fully rescued by the coexpression of SKA3 or DTL." (PMID 30402980, 2018). "Both SKA1 and SKA3 were pivotal candidate genes targeted by miR-455-5p and miR-455-3p, respectively, and we hypothesized that the SKA complex was closely involved in RCC pathogenesis and could be regulated by several anti-tumor miRNAs in RCC cells." (PMID 29928475, 2018). "Moreover, relative to tumor-free survival patients, tumor-bearing patients significantly expressed high levels of SKA1 and SKA3 and both of them did not corelate with advanced pathological T (T3/4)." (PMID 33224872, 2020).
SKA3 also shares sentences with these, for which no sentence is quoted: adenoid cystic carcinoma (1 paper); bladder urothelial carcinoma (1); central nervous system diseases (1); colon cancer (1); hypothyroidism (1); melanoma (1); non-small cell lung carcinoma (1); ovarian carcinoma (1); pheochromocytoma (1); rectal cancer (1); skin cutaneous melanoma (1); toxoplasmosis (1).